SIRT1 (sirtuin 1)
Diseases named in the same sentence as SIRT1 in open-access papers (continued):
Sharing a sentence is not in itself a finding about the gene and the disease.
cancer (continued). "Multiple evidence found that the function of SIRT1 might be tissue or cell specific, and it could act as a tumor suppressor or oncogene in various cancers through regulating different biological pathways." (PMID 35252011, 2022). "SIRT1 was reported to play a crucial role in the development and progression of various cancers." (PMID 35252011, 2022). "However, SIRT1 enzymatic activity can also promote cancer growth by the inactivation of proapoptotic factors." (PMID 36430164, 2022). "SIRT-1 inhibition has been shown to exert a great therapeutic effect in several types of cancers." (PMID 36080416, 2022). "Recent studies have shown that the absence of SIRT1 can cause sphingomyelin to accumulate in cells, and in different cancer types or under different experimental conditions, SIRT can act as an oncogene or a tumor suppressor gene." (PMID 35846357, 2022). "Thus, the current study is the first to demonstrate that Elaiophylin has a potent anti-cancer effect against UM, which activity is possibly mediated through regulating SIRT1-FoxO3a signaling axis." (PMID 35387119, 2022). "SIRT-1 pharmacological activation was also demonstrated to have anti-cancer effects." (PMID 36080416, 2022). "SIRT1 may facilitate cancer progression by epigenetically modulating the polycomb repressor complex 4 (PRC4) comprising DNMT1, DNMT3b, polycomb group (PcG) proteins, embryonic ectoderm development isoform 2 (EED2), and enhancer of zeste homolog 2 (EZH2)." (PMID 35054489, 2022). "The results showed that the expression of SIRT1 was significantly amplified in all sensitive and resistant cancer cells following the treatment with curcumin at concentrations of 54.3 μM and significantly amplified in sensitive cells at curcumin at concentrations of 2.71 μM." (PMID 36143462, 2022). "Intrathecal administration of SRT1720, a SIRT1 agonist, increases SIRT1-mediated mitochondrial biogenesis and decreased spinal cord DRP1 expression, which was associated with a reduction in cancer-induced bone pain and chronic construction injury-induced neuropathic pain." (PMID 36324872, 2022). "The survival function of SIRT1 may reflect abnormal cancer metabolism and identifies SIRT1 as a target for anticancer therapy." (PMID 35350833, 2022). "SIRT1 was the first family member to be recognized as a crucial epigenetic regulator of genomic stability, aging, apoptosis, and senescence in normal cells, as well as a dual regulator in cancer cells." (PMID 36361680, 2022). "Localisation of SIRT1 to the mitochondria following exercise may also occur, with one study in a human carcinoma cell line finding SIRT1 co-localised with PGC-1α and TFAM in the inner matrix." (PMID 35163441, 2022). "In carcinoma, OA could increase ROS level, induce apoptosis, suppress angiogenesis and enhance mitochondrial dysfunction via inactivating sirtuin 1 (SIRT1)-forkhead box O3 (FOXO3)-BNIP3 axis." (PMID 36081929, 2022). "The interaction between PLD2 and Sirt1 is required for protection of cancer cells from apoptosis." (PMID 34471223, 2021). "Accumulating evidence has supported that SIRT1 is involved in tumorigenesis and cancer development." (PMID 34381712, 2021). "In these diseases, the SIRT-1 expression is reduced, while in some cancers, the SIRT-1 expression is significantly increased, suggesting that it may be used for cancer treatment." (PMID 34315467, 2021). "Moreover, activated SIRT1 functions as an inhibitor of Tet2-mediated MDS cell growth, while the SIRT1/Tet2 axis regulates a series of cancer-related genes." (PMID 34222235, 2021).
cancer (continued). "The inhibition of SIRT1 induces growth arrest and apoptosis in several types of cancer cells." (PMID 34150879, 2021). "In cancer cells, dysregulated c-Myc and SIRT1 promote an indefinite cell." (PMID 34222486, 2021). "Recently, we found that SIRT1 preserves genomic stability by preventing the activation of latent origins of replication, suggesting that SIRT1 might affect gene amplification in cancer cells." (PMID 33539925, 2021). "In these cancer cells, active SIRT1 is obviously anti-apoptotic and, thus, cancer promoting." (PMID 34279445, 2021). "Importantly, USP22 was reported to stabilize SIRT1 by deubiquitination to promote autophagy in cancer cells and also protect against ischemia–reperfusion injury in cardiomyocytes." (PMID 34759275, 2021). "Studies related to metabolic disorders and cancer suggest that in addition to activators, finding inhibitors of SIRT1 could be equally useful." (PMID 33669990, 2021). "SIRT1 signaling may be targeted therapeutically to regulate the Th9 cell and Treg cell balance in asthma and cancer." (PMID 33748292, 2021). "The micro-regulation of SIRT1 mRNA by different miRNA has a variety of functions in different cells and tissues, including from physiology and metabolism to disease pathologies such as cardiovascular disease and cancer." (PMID 34616289, 2021). "In addition, butyrate treatment inhibited cancer cell migration via downregulation of HDACs including SIRT1 expression." (PMID 35096835, 2021). "Therefore, knocking down SIRT1 exerts positive feedback in cancer treatment, revealing that SIRT1 is an potential target for cancer treatment." (PMID 34395273, 2021). "To investigate whether the effect of SIRT1 and CUL4B could be extended to a broader scope of cancers, we collected several carcinoma samples on which we performed tissue microarrays and immunohistochemical staining to examine SIRT1 and CUL4B expression." (PMID 34163012, 2021). "Pharmacological blockade of NADPH oxidase 4 (nox4), a key regulator of reactive oxygen species in muscle, significantly abrogated cancer cachexia in mice; targeting the SIRT1-nox4 axis seems to be an effective therapeutic intervention for mitigating cancer cachexia." (PMID 34262449, 2021). "Pharmacological activators are also available and may be applied in those cancer types where SIRT1 is instead downregulated." (PMID 34885146, 2021). "In addition, NAMPT regulation of cancer stem cell pathways correlated with SIRT1 and PARP1, as these proteins seem to play important roles in the CSC phenotype acquisition promoted by NAMPT." (PMID 33384409, 2021). "Interestingly, elevated levels of LAMA4 and LAMC1 are observed in cancer cells, which suggests that their upregulation in SIRT1-depleted adipocytes reflects their hyperplastic phenotype." (PMID 33854178, 2021). "In human cancers, it is presently unclear whether increased SIRT1 or SIRT2 expression irritates or obstructs the forming and/or preservation of malignancy." (PMID 33705642, 2021). "Oppositely, the fact that further studies have displayed reduced SIRT1 level in some types of cancer together with its relevant role in counteracting oxidative stress and maintaining genome integrity, suggested that it may also act as tumor suppressor." (PMID 33917352, 2021).
cancer (continued). "It was suggested that resveratrol, a polyphenol found in grapes, could act as an activator of SIRT1 to protect against oxidative damage, inflammation, and cancer." (PMID 33927645, 2021). "We found just two studies analyzing SIRT1 serum levels in other types of cancer." (PMID 34942940, 2021). "The effects of Sirt6 and Sirt1 combine to regulate ROS-induced cancer cell death." (PMID 33727672, 2021). "Depending on the nature and level of the stresses in specific cancer cells, inhibiting SIRT1 may produce pro-tumor or anti-tumor activity." (PMID 34650436, 2021). "Furthermore, the Sirt1 AS transcript was down-regulated in human tumours, while the Sirt1 mRNA level was increased in cancer cell lines and cancer tissues." (PMID 34575829, 2021). "Meanwhile, homozygous deletion of SIRT1 promoted apoptosis and delayed cancer formation." (PMID 34650436, 2021). "SIRT1 could either promote or inhibit cancer progression, depending on the specific molecular target or cancer type." (PMID 33539925, 2021). "Whether the activated SIRT1-AMPK signaling pathway partially arises from the suppressed aerobic glycolysis in KSHV-induced cancer cells and whether other SIRTs also mediate the survival of KSHV-infected cells and KSHV life cycle remain unknown." (PMID 34579773, 2021). "Sirt6 also influences MDM2 to suppress Sirt1 activity, thereby also promoting cancer cell death." (PMID 33727672, 2021). "Since the expression of PLD2 and SIRT1 is upregulated in various cancers, the interaction between proteins may be increased in cancers and contribute to antiapoptotic function." (PMID 34471223, 2021). "Furthermore, the selective Sirt1 inhibitor the indole EX-527 shows a significant effect in distinct types of cancer, as monotherapy or combined to cancer drugs." (PMID 33024443, 2020). "In cancer, SIRT1 might play a promotional or suppressive role, depending on the cancer type and organs involved." (PMID 32489467, 2020). "Previously, numerous studies have demonstrated that SIRT1 may serve as either a tumor suppressor or promoter in tumorigenesis, depending on cancer type or context, and this finding remains under debate." (PMID 32636443, 2020). "Since SIRT1 has been reported to be involved in tumor initiation and progression as well as cancer stemness, we hypothesized that SIRT1 might be a potential target of SIRT4." (PMID 32863939, 2020). "Consistent with the cooperative action between SIRT1 and SIRT6, independent studies have revealed an interaction between SIRT1 and SIRT7, showing that SIRT1 recruits SIRT7 to promote cancer cell metastasis, and that SIRT1 and SIRT7 antagonistically regulate adipogenesis." (PMID 32538779, 2020). "However, there are no direct evidences showing a role for melatonin in regulating cancer cell growth through SIRT1/circadian clock axis." (PMID 33042011, 2020). "However, it was also shown, that Sirt1 can have tumor suppressing properties and in some instances even a dual role for the same cancer type has been reported." (PMID 32426286, 2020). "Moreover, anti-cancer agent etoposide-induced genotoxic-mediated cancer cell apoptosis has been shown to correlate with both SIRT1 and SIRT3 over-expression." (PMID 32252351, 2020). "Importantly, Sirt1 mediates the mitochondrial metabolic pathway that is activated in various cancers, which not only promotes mitochondrial biogenesis, but also plays a crucial role in cancer development." (PMID 32570218, 2020). "(i) SIRT1 can be overexpressed or underexpressed in different sorts of human cancers." (PMID 32607257, 2020). "The activation of SIRT1 causes the induction of oxidative phosphorylation, which enables cancer cells to become resistant to non-lethal chemotherapy drugs (a hallmark of CSCs)." (PMID 32503256, 2020). "Nevertheless, the function of SIRT1 in cancer is context dependent." (PMID 32051395, 2020). "Several evidence have confirmed that BRCA1 is a key regulator of Sirt1 in cancer research." (PMID 32381096, 2020).
cancer (continued). "Likewise, other finding also showed that SIRT1 inhibition leads to the inhibition of cell proliferation and induction of cancer cell apoptosis." (PMID 32607257, 2020). "A simple scenario is that SirT1 activators may impart cancer prevention effects by enhancing the growth-inhibitory effect of SirT1 in benign tumors." (PMID 32366137, 2020). "Whole-body SIRT1 expression in mice has previously been shown to reduce the onset of cancer although its role in life span increase remains unclear." (PMID 31220223, 2020). "SIRT1 plays a critical role in the regulation of various metabolic and pathophysiological processes, such as glycometabolism and lipid metabolism, inflammation, senescence, apoptosis, DNA damage repair, autophagy, oxidative stress, and cancer." (PMID 32596298, 2020). "In addition, siRNA-mediated depletion of SIRT1 re-sensitizes cisplatin-resistant cancer cells to cisplatin." (PMID 32151067, 2020). "Furthermore, epigenetic regulation of Sirt mRNA, particularly Sirt-1, by non-coding MicroRNAs (miRNAs) is believed to play a prominent role in cell proliferation, development and cancer formation." (PMID 32733649, 2020). "In addition, a moderate decrease in the key regulator of muscle mitochondrial oxidative metabolism and stress defence, NAD+ -dependent Sirt1, was observed in cancer cachexia, as was shown in TB-mice in relation to the severity of cancer cachexia." (PMID 32599075, 2020). "In several cancer models, melatonin inhibits SIRT1 activity." (PMID 33042011, 2020). "SIRT1-mediated survival of cancer cells contributes to chemoresistance in tumors." (PMID 31956359, 2020). "Therefore, SIRT1 inhibition appears to be a good strategy to overcome cancer drug resistance and improve therapy." (PMID 32398958, 2020). "In cancer pathology, it has been reported that SIRT1 regulates tumor growth." (PMID 32489686, 2020). "In fact, Sirt1 was a target of miR-135a in mESCs and cancer cells." (PMID 32335545, 2020). "Nonetheless, dual SIRT1/2 inhibitors showed anti-cancer activity." (PMID 31973227, 2020). "SIRT1 is the NAD-dependent class III deacetylase and strongly implicated in various pathophysiological process, including neurodevelopment, aging, stress, inflammation, and cancer." (PMID 33381265, 2020). "Studies have suggested that nicotine/nAChR axis and SIRT1/3/5-7 mediates cancer drug resistance." (PMID 31956359, 2020). "Though completely different conclusions were reached, these findings strengthen the hypothesis that the SIRT1 promotion or inhibition of cancer migration and invasion is cellular context-dependent." (PMID 31068761, 2019). "Moreover, O-GlcNAcylation mediated SIRT1 stability in cancer cells directly affected the proteasome degradation of oncogenic transcription factor FOXM1." (PMID 31881804, 2019). "SIRT1 plays a critical role in skin homeostasis, aging, and cancer." (PMID 31779194, 2019). "Identifying the precise function of SIRT1 in tumorigenesis helps to develop anti-cancer therapy." (PMID 31598701, 2019). "The example of miR-24, which is suppressed by melatonin, but enhances SIRT1 expression, may be taken as a tumor-specific relationship, because this would conform to melatonin’s known suppression of SIRT1 in cancer cells." (PMID 30862067, 2019). "Although these result suggest that SIRT1 may play a limited role in the effects of CR on cancer, the possible involvement of other sirtuins in the diet-induced effects on tumorigenesis has yet to be elucidated." (PMID 31970087, 2019). "The findings of these studies suggested that once cancer cells acquire the ability to produce SIRT1, the presumed function of SIRT1 may promote the survival of carcinoma cells." (PMID 31101119, 2019). "Furthermore, Overexpression of SIRT1 is found to promote cancer development and implicate poor prognosis in cancer patients." (PMID 31056532, 2019).
cancer (continued). "Sirt1 is a highly conserved NAD+-dependent deacetylase that is widely expressed in various cells and implicated in growth development, energy metabolism, and cancer progression." (PMID 31038546, 2019). "SIRT1 is a downstream effector of the c-Myc and is activated in several cancers." (PMID 31689236, 2019). "Thus, SIRT1/ROS/JNK pathway is one of the important signals that regulates cell apoptosis in cancers." (PMID 31056532, 2019). "Therefore, the anti-cancer effects of Rsv are mediated through Sirt1 activation, SPHK inhibition, and tubulin destabilization." (PMID 31817453, 2019). "Besides, a growing body of evidence suggests that SIRT1 is involved in cancer cell drug resistance through a variety of mechanisms." (PMID 30710424, 2019). "Rsv also reduced HepG2 cancer cell migration and proliferation through Sirt1 activation." (PMID 31817453, 2019). "One reason could be the aberrant expression of the NAD-dependent deacetylase SIRT1, which regulates cancer drug resistance." (PMID 31430957, 2019). "Chu et al30 reported that SIRT1 was upregulated in drug‐resistant cancer cell lines and patients’ tumor samples through increasing expression level of multidrug resistant protein 1, which was reminiscent of SIRT1’s promoting effect in the sensitivity of chemotherapy drugs." (PMID 30697969, 2019). "SIRT1 activators can ameliorate the course of cancers or function as inhibitors of cancer cells." (PMID 29991742, 2018). "Furthermore, SIRT1 is also a reported molecular target of RSV in cancer cells of both lymphoid and epithelial origin." (PMID 30319549, 2018). "The role of Sirt1 in cancer remains unclear probably in consequence of the heterogeneity that characterizes the disease." (PMID 30304806, 2018). "However, the role of SIRT1 in cancer remains controversial; SIRT1 has been shown to play both a pro- and an anti-tumor role in cancer bio-behavior." (PMID 29416748, 2018). "For instance, upregulation of SIRT1 has been reported in multiple cancer cell lines, indicating that SIRT1 inhibitor may be useful as therapeutic agents." (PMID 29401749, 2018). "Interestingly, such induction contributed specifically to enhanced cancer cell survival and proliferation, as it was reversed by the use of SIRT1 inhibitors or GPER silencing as well." (PMID 30319540, 2018). "Furthermore, there are pieces of evidence suggesting that Sirt1 plays a critical role in cardiovascular diseases, metabolic and health span, neurodegenerative diseases, cancer, and optic neuritis." (PMID 29643977, 2018). "Moreover, Overexpression of SIRT-1 was reported to contribute to chemoresistance in several cancers." (PMID 29552311, 2018). "Finally, the authors demonstrated that miR-138-5p also counteracts the hypoxia induction in cancer cells through SIRT1 inhibition in tumor xenografts." (PMID 30319549, 2018). "In the context of cancer, SIRT1 has been studied primarily for its role in DNA damage response." (PMID 29717261, 2018). "Cancer models of the secretory organs in which SIRT1 has been studied." (PMID 30319549, 2018). "Using site-directed mutagenesis, a luciferase reporter assay, and immunoprecipitation, we found that CPEB1 could directly target the 3′-UTR of SIRT1, control poly(A) tail length and suppress its translation to mediate cancer stemness in vitro and in vivo." (PMID 30237545, 2018). "It should be noted that SIRT1 plays diverse roles in cancer biology." (PMID 30544833, 2018). "Mechanistically, H19 triggered autophagy via SIRT1 to induce cancer chemoresistance." (PMID 30451820, 2018).